IL10 (interleukin 10)
Diseases named in the same sentence as IL10 in open-access papers (continued):
Sharing a sentence is not in itself a finding about the gene and the disease.
C. perfringens infection (4 papers, 2020 to 2025). "In line with earlier findings in piglets and IPEC-J2 cells, we observed that C. perfringens infection significantly increased the serum levels of IL-1β, IL-6, and TNF-α, while decreasing those of IL-4 and IL-10." (PMID 40427288, 2025). "Compared to the CON group, C. perfringens infection significantly elevated serum levels of IL-1β, IL-6, and TNF-α, while suppressing IL-4 and IL-10 (p < 0.05)." (PMID 40427288, 2025).
cholesteatoma (4 papers, 2021 to 2024). A pathologic process characterized by the proliferation of keratinizing squamous epithelium resulting in the accumulation of keratin and cells in the middle ear and/or mastoid. "The disproportion between IL-1 and IL-10 in cholesteatoma could be one of many causes of its aggressiveness." (PMID 36837507, 2023). "Our data indicated the increased S100A8 and S100A9 were associated with increased IFN-γ and TGF-β but decreased IL-10 in clinical and animal models of EACC, consistent with the pathogenesis mechanism of inflammation involved in cholesteatoma pathogenesis." (PMID 39575241, 2024). "The similarity in the expression of IL-1 and IL-10 suggests the dysregulation of the local immune status in cholesteatoma." (PMID 36837507, 2023). "We showed a similar correlation between HβD-2 and IL-10 (r = 0.663, p = 0.002) in the cholesteatoma perimatrix, where T cells predominate." (PMID 36837507, 2023). "To research inflammation processes in cholesteatoma, we detected pro- and anti-inflammatory cytokines IL-1 and IL-10." (PMID 34682191, 2021). "The main anti-inflammatory cytokine, Interleukin-10 (IL-10), on the other hand, works against high pro-inflammatory cytokine levels in cholesteatoma tissue." (PMID 34682191, 2021). "We chose HβD-2, HβD-4, IL-1 and IL-10 to evaluate the inflammatory process in cholesteatoma." (PMID 36837507, 2023). "In addition, this may suggest cooperation between IL-10 and HβD-2 in anti-inflammatory activity in cholesteatoma." (PMID 38535082, 2024). "In contrast with the strong positive correlation between IL-1α and IL-10 in both groups of cholesteatoma, we found a very strong but negative correlation between IL-1α and IL-10 in the control group." (PMID 38535082, 2024). "Still, IL-10 in the cholesteatoma tissue did not statistically differ from the levels of IL-10 in the external ear canal skin." (PMID 34682191, 2021). "However, we found a strong positive correlation between IL-1 and IL-10 in cholesteatoma tissue and an opposite, very strong negative correlation between IL-1 and IL-10 in the control group." (PMID 34682191, 2021).
chronic atrophic gastritis (4 papers, 2013 to 2025). Atrophic gastritis that is persistent and long-standing. "In this study, PD-MSCs exerted a significant rejuvenating effect against H. pylori–induced atrophic gastritis by regulating the inflammasomes associated with autophagy induction and inducing a significant increase in anti-inflammatory IL-10 production." (PMID 34483897, 2021).
chronic myeloid leukemia (4 papers, 2022 to 2025). "In chronic granulocytic leukemia (CML), an increased number of MDSCs and its immune suppressive markers such as IL10 and ARG1 was observed." (PMID 37091970, 2023).
chronic viral hepatitis (4 papers, 2013 to 2021). "So future studies should continue to explore associations between polymorphisms in IL-10 gene and the risk of other subtypes of viral hepatitis." (PMID 32742307, 2020). "The relationships between polymorphisms in interleukin-10 (IL-10) gene and the risk of viral hepatitis remain inconclusive." (PMID 32742307, 2020). "So a meta-analysis was conducted to robustly analyze the relationships between polymorphisms in IL-10 gene and the risk of viral hepatitis by integrating the results of previous works." (PMID 32742307, 2020). "This meta-analysis, for the first time, robustly assessed associations between polymorphisms in IL-10 gene and the risk of viral hepatitis." (PMID 32742307, 2020). "However, future studies should continue to investigate associations between polymorphisms in IL-10 gene and the risk of other subtypes of viral hepatitis." (PMID 32742307, 2020). "First, based on the findings of previous observational studies, it is believed that the three investigated IL-10 polymorphisms may alter mRNA expression level of IL-10 gene, impact anti-viral immune responses, and then influence the risk of viral hepatitis." (PMID 32742307, 2020). "Therefore, the authors conducted so far the very first meta-analysis to robustly assess the relationships between polymorphisms in IL-10 gene and the risk of viral hepatitis by integrating the results of previous works." (PMID 32742307, 2020). "Secondly, environmental factors may also affect relationships between polymorphisms in IL-10 gene and the risk of viral hepatitis." (PMID 32742307, 2020). "In HBV patients, anti-inflammatory IL-10 in serum has been shown to be elevated and decreases cytokine production by monocytes, suggesting that regulatory mechanisms are in play during chronic viral hepatitis." (PMID 27812182, 2016). "Currently, only INF-alpha is used in the treatment of chronic viral hepatitis because the effectiveness of the exogenous administration of IL12, IL2 and IL10 is unclear." (PMID 24130726, 2013). "A recent meta-analysis showed that IL-10 levels in HCC patients are increased compared to cirrhotic patients and healthy controls, but not to patients with viral hepatitis, thereby adding complexity to the interpretation of IL-10 data for HCC." (PMID 34638361, 2021).
Cough (4 papers, 2012 to 2025). A sudden, audible expulsion of air from the lungs through a partially closed glottis, preceded by inhalation. "Therefore, airway activated IFN‐γ+ T‐lymphocytes and dysregulated cytokines (especially IFN‐γ, TNF‐α, IFN‐α, IFN‐β, and IL‐10) might serve as inflammatory signatures in some patients with postinfectious cough." (PMID 40859955, 2025).
cutaneous melanoma (4 papers, 2007 to 2026). A primary melanoma arising from atypical melanocytes in the skin. "In particular, the expression of IDO increased between primary cutaneous melanoma and negative SLN by median 29.11-fold in five out of seven cases examined (P<0.037), and IL-10 by median 6.37-fold (P<0.047)." (PMID 17565341, 2007). "The observation that the two cutaneous melanoma cell lines exhibit a different expression profile and that the cutaneous melanoma line G361 is similar to the uveal melanoma cell line OCM-1 with respect to IL-10Rα and miRNA expression and responses to IL-10 is not surprising." (PMID 26631117, 2015). "Indeed, the uveal and cutaneous melanoma cell lines OCM-1 and G361, which displayed downregulation of IL-10Rα (with G361 also exhibiting higher IL-10Rβ expression), did not proliferate after IL-10 treatment, as opposed to GR-M cells with moderate IL-10Rα expression." (PMID 26631117, 2015).
demyelination (4 papers, 2017 to 2023). "Overall, our results suggest that IL-6, IL-10 or TGF-β are not required for TH17 cell induced demyelination and expression of IL-2 by HSV-IL-2 plays an important role in the generation of pathogenic TH17 cells as was reported previously." (PMID 36817487, 2023).
diarrhoea (4 papers, 2010 to 2023). "Vitamin D–deficient IL-10-deficient mice developed diarrhoea and a wasting disease." (PMID 28294972, 2017).
diphtheria (4 papers, 2016 to 2024). A Gram-positive bacterial infection caused by Corynebacterium diphtheriae. "In the 2006–2009 cohort, IL-10 immunomodulatory cytokine responses to filaria and to S. haematobium were significantly associated with reductions in Hib and diphtheria vaccine responses and/or duration of effect." (PMID 30818339, 2019). "In addition to being positively correlated with schistosome‐induced IL‐10 levels, maternal schistosome infection has been linked to reduced protective IgG antibody formation to the Hemophilus influenzae type b (Hib) and diphtheria toxoid (DT) vaccinations." (PMID 39560407, 2024).
diverticulosis (4 papers, 2014 to 2022). "The release of IL-10 by biopsies was evaluated in patients with diverticulosis, SUDD, SUDD subsequent to previous acute diverticulitis and asymptomatic controls." (PMID 35743141, 2022). "In particular, mean IL-10 expression was 3.32 (95% CI 0.43-7.91) pg/g in HC, 3.42 (95% CI 1.87-5.10) pg/g in asymptomatic diverticulosis, and 4.24 (95% CI 1.90-7.53) pg/g in SUDD." (PMID 31001067, 2019). "Using an Enzyme-Linked Immunosorbent Assay (ELISA) analysis on fecal samples, we found an increased release of IL-10 from HC up to asymptomatic diverticulosis and SUDD patients." (PMID 31001067, 2019). "The assessment of IL-10 in the feces of healthy subjects, diverticulosis, and SUDD, revealed an increase in this anti-inflammatory cytokine amount in both groups of patients with diverticula, irrespective of the presence of symptoms, although the statistical significance was not determined." (PMID 35743141, 2022).
Duchenne muscular dystrophy (4 papers, 2021 to 2023). Duchenne muscular dystrophy (DMD) is a neuromuscular disease characterized by rapidly progressive muscle weakness and wasting due to degeneration of skeletal, smooth and cardiac muscle. "A study performed in muscle cells obtained from a mouse model of Duchenne muscular dystrophy revealed that the treatment with AdipoRon augmented the expression of IL-10 mRNA and protein as compared to untreated animals." (PMID 34084174, 2021). "Our results corroborate previous findings that reported IL-10 ablation significantly slowed myogenesis in regenerating muscle during acute injury or chronic disease (i.e., Duchenne Muscular Dystrophy, DMD), showing a lower growth of new muscle fibers and poor resilience to damage." (PMID 37048088, 2023). "In addition, IL-10 secreting MSCs demonstrated enhanced cell survival and therapeutic benefits in models for Duchenne muscular dystrophy (DMD)." (PMID 36362383, 2022).
epileptic seizures (4 papers, 2019 to 2025). "The plasma elevation of proinflammatory cytokines (IL-1; IL-6; TNF-alpha; INF-gamma), which is traditionally associated with epileptic seizures, is countered by the elevation of anti-inflammatory mechanisms (IL-10; Fractalkine; GCSF) and the decrease in plasma concentration of IGF-1." (PMID 40076950, 2025).
esophagitis (4 papers, 2010 to 2024). An acute or chronic inflammatory disease affecting the esophageal wall. "We found that patients with at least one variant allele of IL10:rs1800872 had a 1.74-fold increased risk of esophagitis, but a 40% decreased risk of dying when compared to patients with wild-type genotypes (HR:0.62, 95% CI:0.40–0.97)." (PMID 20811626, 2010). "SNPs in the IL4 receptor, IL10, and the alpha subunit of the IL10 receptor were found to be significantly associated with increased esophagitis risk." (PMID 20811626, 2010). "Furthermore, we identified one variant in IL10 that is associated with increased risk of esophagitis, but a decreased risk of dying." (PMID 20811626, 2010). "The effects of inhibitors of H2S synthesis or of an H2S donor on severity of esophagitis was then examined, along with changes in serum levels of a pro- and an anti-inflammatory cytokine (IL-17 and IL-10, respectively)." (PMID 25333941, 2014). "Treatment with L-Trp, which attenuated the detrimental effects of PAG in the esophagitis model, modestly increased serum IL-10 levels but did not affect serum IL-17 levels." (PMID 25333941, 2014).
febrile seizures (4 papers, 2011 to 2025). "In this study, we explored the distribution of IL-10 gene polymorphisms and their correlation with febrile seizure (FS) susceptibility among children in the Wenzhou region of Zhejiang Province." (PMID 40832036, 2025). "Two proteins identified in this study have been described in human genetic studies before: single nucleotide polymorphisms (SNPs) present in IL-1α and IL-10 genes are associated with TLE and febrile seizures respectively." (PMID 22935090, 2012). "Peripheral blood mononuclear cells from febrile seizure patients have shown increased IL-10 production by LPS." (PMID 21989210, 2011). "Febrile seizure patients without a family history of febrile seizures showed a 3.5-fold increase of IL-10 levels (p < 0.05) above the fever only controls and a 3.7-fold increase above those with FS without a family history of febrile seizures (p = 0.31)." (PMID 21989210, 2011).
fibrosarcoma (4 papers, 2013 to 2022). A malignant mesenchymal fibroblastic neoplasm affecting the soft tissue and bone. "qRT-PCR revealed that the levels of mRNA for the proinflammatory cytokines Ifng, Il1b, and Il12b and the anti-inflammatory cytokine Il10 in fibrosarcomas induced by 5 μg MCA were similar in WT and CD155-deficient mice in both C57BL/6N and BALB/c backgrounds." (PMID 25384044, 2014).
Gastric Diseases (4 papers, 2011 to 2019). "Recently, the polymorphism of proinflammatory cytokines such as IL1RN and anti-inflammatory cytokines such as IL-10 has been implicated in clarifying host factors in the development of gastric diseases." (PMID 31885568, 2019). "Furthermore, the low IL-10 levels were insufficient to modulate the Helicobacter-specific Th1 immune response and may cause severe inflammation and hyperresponsiveness in the gastric lumen, leading to gastric diseases." (PMID 22526791, 2012). "One of the most prominent modes of mediation of indomethacin-induced gastropathy is the increased expression of the pro-inflammatory cytokines, as well as reducing the anti-inflammatory cytokines (IL-10) at the mucosal level." (PMID 21076542, 2011).
glomerulosclerosis (4 papers, 2015 to 2021). A hardening of the kidney glomerulus caused by scarring of the blood vessels. "The high-fat dieted mice showed increased serum creatinine, BUN and proteinuria, which means renal endothelial cell dysfunction by the glomerulosclerosis and tubulointerstitial fibrosis and IL-10 deficiency worsens them." (PMID 33547567, 2021). "In normal kidneys, IL-10 reduces inflammation, mesangial cell proliferation, glomerulosclerosis and interstitial fibrosis." (PMID 33547567, 2021). "IL-10, a potent anti-inflammatory cytokine, was reported to inhibit inflammation, glomerulosclerosis progression, and interstitial fibrosis and improve renal function in CKD." (PMID 26640497, 2015). "In addition, increased IL-10 levels decreased proteinuria and reduced interstitial fibrosis and glomerulosclerosis in a 5/6 nephrectomized rat model." (PMID 26489007, 2015).
gram-negative bacterial infections (4 papers, 2020 to 2025). Infections caused by bacteria that show up as pink (negative) when treated by the gram-staining method. "In our experiment, the IL-10 levels were higher in response to Gram-negative bacterial infections compared to Gram-positive ones." (PMID 40873569, 2025). "Several studies using LPS as a model of a Gram-negative bacterial infection have indicated that IL-10 administration prevents preterm birth in rodent models." (PMID 37747229, 2023).
H1N1 influenza (4 papers, 2011 to 2023). "It has been reported that pregnant women infected with H1N1 influenza had significantly higher serum levels of IL‐6, IL‐10 and TNF‐α than healthy pregnant women, and IL‐6 was correlated with the severity of the disease." (PMID 37638092, 2023). "With disease progression, higher levels of sera IL-6 and IL-10 were found in severe pandemic H1N1 influenza patients." (PMID 22174866, 2011). "For instance, melatonin was found to exhibit therapeutic potential in influenza A H1N1 virus infection, to elicit anti-inflammatory and immune modulatory effects—the induction of IL-10 by melatonin occurs via the upregulation of IL-27 in DC—and to exhibit a synergistic effect with an antiviral drug." (PMID 32911682, 2020).
Heat Stroke (4 papers, 2014 to 2024). A condition caused by the failure of body to dissipate heat in an excessively hot environment or during PHYSICAL EXERTION in a hot environment. "Therefore, in the present study, we investigated changes in serum concentrations and clearance of the pro-inflammatory factors TNF-α and IL-6 and the anti-inflammatory factor, IL-10, in dogs following the induction of heat stroke and HF." (PMID 25145441, 2014). "The research reveals that heat stroke triggers an early and complex systemic inflammatory response, marked by the simultaneous release (rather than a sequential release) of pro‐inflammatory cytokines such as IL‐6 and IL‐8, and anti‐inflammatory cytokines like IL‐10." (PMID 38124439, 2024). "Serum concentrations of all solutes tended to increase with time after heat stroke in the control group, but decreased (BUN, creatinine) or remained relatively unchanged (TNF-α, IL-6, IL-10) with time in the HF group." (PMID 25145441, 2014). "Of note, during the 1 to 3 hour post-heat stroke induction period, serum concentrations of TNF-α, IL-6, IL-10, BUN, and creatinine were significantly lower in dogs that received HF than in dogs that did not receive HF." (PMID 25145441, 2014). "We found that in the 3 hours after the induction of heat stroke, serum concentrations of TNF-α, IL-6, IL-10, BUN, and creatinine continued to increase in the control group of dogs, but not in the group of dogs that subsequently received HF." (PMID 25145441, 2014). "Serum concentrations of interleukin (IL)-10, tumor necrosis factor (TNF)-α, IL-6, blood urea nitrogen (BUN) and creatinine were measured at baseline and 1, 2, and 3 h after heat stroke." (PMID 25145441, 2014). "In addition, administration of human umbilical cord blood cells (HUCBC) also increases the serum levels of IL-10 and decreases the levels of TNF-α during heat stroke." (PMID 32477247, 2020). "HF prevents heat stroke-induced increases in serum cytokine concentrations and is effective for clearing small molecular weight solutes from serum, but less effective for clearing larger molecular weight solutes, including TNF-α, IL-6, and IL-10." (PMID 25145441, 2014).
hemorrhagic stroke (4 papers, 2016 to 2022). A stroke caused by a bleed on the brain. "Additionally, IL-6 and IL-10 levels were higher in hemorrhage stroke patients with 1-month unfavorable outcomes." (PMID 36439158, 2022).
Hepatomegaly (4 papers, 2009 to 2024). Abnormally increased size of the liver. "Accordingly, we demonstrated that the F3 peptide vaccine was capable of increasing the IDR and the ratios of TNF-α/IL-10 CD4+ T cells and of decreasing the parasite load and hepatomegaly." (PMID 21085470, 2010). "Also similar to what has already been reported the ratios of IFN-γ/IL-10 producing CD4 T cells were not correlated to the decrease of LDU or hepatomegaly (p>0.05), but were correlated to the increase of IDR, CD4+ T cells and IgG, IgG2a and IgG2b antibodies (p<0.023 for all variables)." (PMID 21085470, 2010).
herpes simplex encephalitis (4 papers, 2011 to 2023). Herpes simplex virus encephalitis (HSE) is caused by the infection of the central nervous system by Herpes simplex virus (HSV) that could have a devastating clinical course and a potentially fatal outcome particularly with delay or lack of treatment. "For example, B. fragilis expresses the capsular polysaccharide A (PSA) to induce CD4+ T-cell-dependent immune response and activates immunomodulatory IL-10, exhibiting anti-inflammatory effects during herpes simplex encephalitis." (PMID 37235443, 2023). "Here Ramakrishna and colleagues show that PSA administration in a murine model of herpes simplex encephalitis induces IL-10 producing B and T cell populations that confer protection against lethal challenge and brain pathology." (PMID 31089128, 2019). "PSA reduces brain stem inflammation and prevents fatal herpes simplex encephalitis (HSE) by binding to enteric-resident plasma blasts and inducing secretion of IL-10 and gamma-interferon (IFNγ) by CD4+T cells and CD8+T cells." (PMID 36992112, 2023).